ZNF565 (zinc finger protein 565)
Description:
May be involved in transcriptional regulation.
Synonyms: FLJ36991
Tractability: PROTAC: ubiquitination databases record sites on it.
Gene: Protein-coding gene on chromosome 19 (36,181,542 to 36,246,257, reverse strand). Ensembl gene ENSG00000196357.
Subcellular location: Nucleus
Subcellular location (Human Protein Atlas): Nuclear bodies; Nucleoplasm
Pathways (Reactome):
Gene expression (Transcription): Generic Transcription Pathway
Gene Ontology:
Molecular function: DNA-binding transcription factor activity, RNA polymerase II-specific; RNA polymerase II cis-regulatory region sequence-specific DNA binding
Biological process: regulation of transcription by RNA polymerase II; regulation of DNA-templated transcription
Cellular component: nucleus
Genetic constraint (gnomAD): Loss-of-function variants: 33 observed, 46.3 expected, observed/expected ratio (o/e) 0.71, 90% interval 0.54 to 0.95. The upper end of that interval is the gene's LOEUF score, 0.95, which puts it in group 4 of 6, group 1 being the genes least tolerant of losing a copy. Missense variants: 524 observed, 654.19 expected, observed/expected ratio (o/e) 0.8, 90% interval 0.75 to 0.86. Synonymous variants: 185 observed, 227.88 expected, observed/expected ratio (o/e) 0.81, 90% interval 0.72 to 0.92.
Homologues: Orthologues: chimpanzee ZNF565 (99% identical), macaque ZNF565 (98% identical), dog ZNF565 (90% identical), pig ZNF565 (90% identical), rabbit ZNF565 (88% identical). Paralogues in human: ZNF461 (57% identical), ZFP14 (54% identical), ZNF571 (53% identical), ZFP30 (51% identical), ZNF540 (51% identical), ZFP82 (50% identical), ZNF546 (49% identical), ZNF573 (49% identical), ZNF841 (48% identical), ZNF30 (47% identical), ZNF267 (46% identical), ZNF585B (46% identical), and 164 more.
Diseases named in the same sentence as ZNF565 in open-access papers:
ZNF565 is named in the same sentence as 1 disease in open-access papers, as found by Europe PMC text mining. Sharing a sentence is not in itself a finding about the gene and the disease. The quoted sentences say what the papers report.
cancer (1 paper, 2017). A tumor composed of atypical neoplastic, often pleomorphic cells that invade other tissues. "The role of ZFR and ZNF565 in cellular proliferation and survival, especially in cancer and in the context of PI3K pathway inhibition, are not yet known." (PMID 28561737, 2017).